RAB4B (RAB4B, member RAS oncogene family)
Description:
The small GTPases Rab are key regulators of intracellular membrane trafficking, from the formation of transport vesicles to their fusion with membranes. Rabs cycle between an inactive GDP-bound form and an active GTP-bound form that is able to recruit to membranes different set of downstream effectors directly responsible for vesicle formation, movement, tethering and fusion (By similarity). RAB4B mediates endosomal tethering and fusion through the interaction with RUFY1 and RAB14. Acts as a regulator of platelet alpha-granule release during activation and aggregation of platelets (By similarity).
Synonyms: FLJ78649; MGC52123
Tractability: Small molecule: a structure with a bound ligand is known. Antibody: UniProt places it where antibodies can reach, with high confidence; its Gene Ontology location is reachable by antibodies, with high confidence. PROTAC: ubiquitination databases record sites on it; its protein half-life has been measured.
Gene: Protein-coding gene on chromosome 19 (40,778,195 to 40,798,690, forward strand). Ensembl gene ENSG00000167578.
Subcellular location: Cell membrane; Early endosome membrane
Pathways (Reactome):
Immune System: Neutrophil degranulation
Metabolism of proteins: RAB geranylgeranylation
Signal Transduction: MET receptor recycling
Gene Ontology:
Molecular function: G protein activity; GTPase activity; protein binding; GTP binding
Biological process: D-glucose import across plasma membrane; early endosome to Golgi transport; endosomal vesicle fusion; regulation of endocytosis; vesicle-mediated transport; Rab protein signal transduction
Cellular component: early endosome membrane; insulin-responsive compartment; perinuclear region of cytoplasm; recycling endosome; plasma membrane; secretory granule membrane; cytoplasmic vesicle membrane; cytosol
Genetic constraint (gnomAD): Loss-of-function variants: 15 observed, 27.41 expected, observed/expected ratio (o/e) 0.55, 90% interval 0.37 to 0.84. The upper end of that interval is the gene's LOEUF score, 0.84, which puts it in group 3 of 6, group 1 being the genes least tolerant of losing a copy. Missense variants: 244 observed, 292.11 expected, observed/expected ratio (o/e) 0.84, 90% interval 0.75 to 0.93. Synonymous variants: 108 observed, 119.35 expected, observed/expected ratio (o/e) 0.9, 90% interval 0.77 to 1.06.
Homologues: Orthologues: chimpanzee RAB4B (100% identical), dog RAB4B (100% identical), guinea pig RAB4B (100% identical), macaque RAB4B (100% identical), mouse Rab4b (99% identical), pig RAB4B (97% identical), zebrafish rab4b (92% identical), rat Rab4b (89% identical), tropical clawed frog rab4b (85% identical), Drosophila melanogaster Rab4 (75% identical). Paralogues in human: RAB4A (87% identical), RAB14 (57% identical), RAB2B (52% identical), RAB2A (51% identical), RAB11B (46% identical), RAB11A (44% identical), RAB43 (42% identical), RAB25 (41% identical), RAB1B (40% identical), RAB1A (40% identical), RAB37 (39% identical), RAB18 (39% identical), and 56 more.
Diseases named in the same sentence as RAB4B in open-access papers:
RAB4B is named in the same sentence as 17 diseases in open-access papers, as found by Europe PMC text mining. Sharing a sentence is not in itself a finding about the gene and the disease. The quoted sentences say what the papers report.
diabetes (2 papers, 2009 to 2021). "Altogether, our results documents Rab4b as the first Rab protein which co-localize in adipocytes with GLUT4 in its sequestration compartments which is modulated in diabetes." (PMID 19590752, 2009).
Insulin resistance (2 papers, 2021 to 2024). Increased resistance towards insulin, that is, diminished effectiveness of insulin in reducing blood glucose levels. "As obesity affects T cells in adipose tissue, Rab4b levels may decrease, leading to insulin resistance and dysfunctional adipose tissue." (PMID 39338478, 2024).
Obesity (2 papers, 2024). Accumulation of substantial excess body fat. "Rab4b, a small GTPase governing endocytic trafficking in T cells, exhibits decreased expression in individuals with obesity, which may also contribute to the elevation of Th17 cells and reduction of Tregs within AT in obesity." (PMID 38455510, 2024).
breast carcinoma (1 paper, 2023). "In a different cell type, BT20 breast cancer cells, knockdown of Rab4a, Rab4b, Rab11a, Rab11b or Rab25 significantly decreased motility, as did knockdown of CLINT1 or SH3BP5L." (PMID 37232246, 2023).
Corynebacterium infection (1 paper, 2024). "Some scholars have shown that Rab4b transcription is upregulated 12-fold after 4 h of Corynebacterium infection." (PMID 39330865, 2024).
depression (1 paper, 2021). "Rab4B protein expression is decreased in the brains of depression sufferers." (PMID 35280519, 2021).
HCMV infection (1 paper, 2018). "While RAB4B is clearly necessary for successful virus production, these results paradoxically suggest that RAB4B activity hinders early events in HCMV infection." (PMID 29946045, 2018). "In infected cells, RAB4B staining clearly colocalizes with pp28 in the VAC, demonstrating relocation of RAB4B to the VAC at late stages of HCMV infection." (PMID 29946045, 2018).
triple-negative breast carcinoma (1 paper, 2023). An invasive breast carcinoma which is negative for expression of estrogen receptor (ER), progesterone receptor (PR), and human epidermal growth factor receptor 2 (HER2). "We next sought to confirm our findings using BT20 triple-negative breast cancer cells, which express Rab4a, Rab4b, Rab11a, Rab11b and Rab25." (PMID 37232246, 2023).
virus infection (1 paper, 2018). "Surprisingly, knockdown also results in a reproducible increase in early GFP reporter expression in the first screen, suggesting increased levels of infection or translocation and a possible antagonistic role for RAB4B activity in the initial stages of virus infection." (PMID 29946045, 2018). "Knockdown of RAB4B resulted in an initial increase in immediate early expression, corresponding with the increase in GFP expression at early time points and supporting the notion that RAB4B has a negative impact on early events in virus infection." (PMID 29946045, 2018).
infection (5 papers, 2018 to 2025). The state of being infected such as from the introduction of a foreign agent such as serum, vaccine, antigenic substance or organism. "Rab4b was identified as a host factor associated with GpCDT infection in our previous study." (PMID 39330865, 2024). "This work establishes a framework for further investigation into the precise mechanism by which Rab4b affects the progression of GpCDT infection." (PMID 39330865, 2024). "The mechanisms we identified contribute to a deeper understanding of how GpCDT utilizes the Rab4b protein to facilitate infection, and may aid in the development of new strategies to control bacterial infections." (PMID 41244687, 2025). "Therefore, we speculated that Rab4b is crucial to the infection of PK-15 cells by GpCDT." (PMID 39330865, 2024). "Finally, we show that RAB4B relocates to the viral assembly compartment following infection with HCMV and knockdown of RAB4B reduces the release of intact virion particles, suggesting that it plays a role in virion assembly and egress." (PMID 29946045, 2018). "Additionally, Rab4b and EEA1 also play a crucial role in the virus’s infection." (PMID 41244687, 2025).
cancer (2 papers, 2014 to 2017). A tumor composed of atypical neoplastic, often pleomorphic cells that invade other tissues. "Some Rabs, such as Rab1b, Rab4b, Rab10, Rab22a, Rab24, and Rab25, are dysregulated in many cancers." (PMID 24587032, 2014). "RAB4B is a small GTPase in the RAS signalling pathway, the dysregulation of which led to cancers in many organs." (PMID 28306719, 2017).
bacterial infection (1 paper, 2025). "Rab4b and EEA1 have been shown to assist bacterial infection." (PMID 41244687, 2025).
RAB4B also shares sentences with these, for which no sentence is quoted: bladder tumors (1 paper); bronchial hyperreactivity (1); familial colorectal cancer (1); lung carcinoma (1); tumor (1).